ANGPTL4 (angiopoietin like 4)
Diseases named in the same sentence as ANGPTL4 in open-access papers (continued):
Sharing a sentence is not in itself a finding about the gene and the disease.
atherosclerosis (continued). "In the genomic regions shared by GlycA and atherosclerosis, five nonsynonymous exonic SNPs were mapped to genes FGB, SLC22A1, LPL, SERPINA1, and ANGPTL4, with the following high PPs, H3: 94.5%, H4: 96.8%, H4: 73.7%, H4: 97.2%, and H4: 100%." (PMID 38892172, 2024). "We provide the proof of concept that liver-targeted anti-Angptl4 ASO treatment strongly attenuates hyperlipidemia and atherosclerosis development, and combined Angptl3/4 silencing has added lipid-lowering benefit." (PMID 39259836, 2024). "Therefore, high ANGPTL4 levels may contribute to atherosclerosis development and progression." (PMID 39728292, 2024). "Therefore, to investigate the effect of ANGPTL4 on inflammatory vascular disease, we performed a comprehensive evaluation of atherogenesis, including inflammatory phenotype and plaque stability, in an Apoe-/- mouse model of high-fat diet-induced atherosclerosis." (PMID 36782020, 2023). "The ANGPTL4 group had less lipid deposition in SMC+ cells in the plaque relative to the PBS group, suggesting that ANGPTL4 effectively reduces the size of the lipid core and VSMC-derived foam cells in advanced atherosclerosis." (PMID 36782020, 2023). "Most study focus on variation and expression of ANGPTL3 or ANGPTL4 in CHD and AMI, less in atherosclerosis." (PMID 34742313, 2021). "The studies indicating that ANGPTL4 may be able to protect against complications of atherosclerosis and CAD have led some to hypothesize that ANGPTL4 may be useful as a potential therapeutic." (PMID 40723247, 2025). "Moreover, in an atherosclerosis mouse model, Nox1 and KLF4 were significantly downregulated in the ANGPTL4 group." (PMID 36782020, 2023). "Since we have shown the cardioprotective effects of anti-inflammatory angiopoietin-like 4 (ANGPTL4) in a mouse model of MI16, we were interested in whether ANGPTL4 could exert a protective function during the development of atherosclerosis." (PMID 36782020, 2023). "Thus, previous studies have revealed the importance of ANGPTL4, which is known as a regulator of LPL in cardiometabolic disorders such as atherosclerosis." (PMID 35566578, 2022). "Increased ANGPTL3 and decreased ANGPTL4 were positively associated with the progression of atherosclerosis, and ANGPTL3 had negative associations with ANGPTL4." (PMID 34742313, 2021). "Lack of Angptl4 in adipose tissue enhances the clearance of proatherogenic lipoproteins, attenuates inflammation, and reduces atherosclerosis." (PMID 33601337, 2021). "We investigated the role of ANGPTL3 and ANGPTL4 in atherosclerosis development and determined whether plasma concentrations of ANGPTL3 and ANGPTL4 are related to the degree of coronary stenosis." (PMID 34742313, 2021). "As the study showed, the concentration of ANGPTL3 was significantly higher and that of ANGPTL4 was obviously lower in the atherosclerosis group than in the nonstenosis group." (PMID 34742313, 2021). "ANGPTL3, ANGPTL4 and smoking status had a statistically significant association with atherosclerosis in both the univariate and multivariate analyses, but the levels of ANGPTL3 and ANGPTL4 were not different between smokers and nonsmokers." (PMID 34742313, 2021). "Likewise, animal models convincingly show that increased clearance of TRLs and RLPs by LPL activation (achieved by inhibition of APOC3, ANGPTL3, or ANGPTL4 action, or increased APOA5) results in protection from atherosclerosis." (PMID 32849290, 2020). "Our results strongly suggest that absence of adipose ANGPTL4 reduces atherosclerosis progression by decreasing circulating proatherogenic lipoproteins, inflammatory cytokines, and vascular inflammation." (PMID 29563332, 2018). "The absence of ANGPTL4 in macrophages has been shown to promote atherosclerosis, inducing foam cell formation and vascular inflammation." (PMID 28182091, 2017). "However, the specific mechanism of action of ANGPTL4 in the occurrence and development of atherosclerosis is not yet distinct." (PMID 34742313, 2021).
atherosclerosis (continued). "Finally, lack of ANGPTL4 in AT enhances the clearance of proatherogenic lipoproteins, attenuates inflammation, and reduces atherosclerosis." (PMID 29563332, 2018).
Insulin resistance (46 papers, 2008 to 2025). Increased resistance towards insulin, that is, diminished effectiveness of insulin in reducing blood glucose levels. "ANGPTL4 mRNA levels in the omental fat were significantly associated with the expression of local markers of inflammation, dysfunction, and insulin resistance." (PMID 33003532, 2020). "Since NAFLD is closely linked to dysregulated lipid metabolism and insulin resistance, ANGPTL4’s involvement in these processes may contribute to the pathogenesis of NAFLD." (PMID 37679750, 2023). "Furthermore, Peptococcaceae was significantly more prevalent and Alistipes was less prevalent in individuals with insulin resistance via influencing serum concentrations of angiopoietin-like 4 and adropin, which was consistent with our causal inference of GM on DNP." (PMID 39157683, 2024). "Specifically, they showed elevated IL1RN (a marker of systemic inflammation), ANGPTL4 (a key regulator of lipid metabolism), DCBLD2 (associated with insulin resistance), and LEP (a hormone for long-term energy balance)." (PMID 40528258, 2025). "ANGPTL4 is a molecular linker between insulin resistance and rheumatoid arthritis and can inhibit LPL activity." (PMID 36790644, 2023). "In mice fed with a high-fat diet, Angptl4 overexpression alleviated glucose intolerance and insulin resistance by promoting insulin signaling via IRS-1 phosphorylation." (PMID 36292250, 2022). "The mRNA expressions of TNF-α, IL-6, and angiopoietin-like 4 (Angptl4), which are involved in insulin resistance, were shown to be higher in the adipose tissue of mice from the P. gingivalis-administered group." (PMID 36299624, 2022). "ANGPTL3 and ANGPTL4 are proteins whose malfunction is related to dyslipidaemia or insulin resistance." (PMID 34947881, 2021). "We showed that VAT ANGPTL4 is increased in obese subjects with impaired glucose regulation and T2D and with insulin resistance." (PMID 33003532, 2020). "VAT ANGPTL4 expression was higher in AGM individuals than in those with normal glucose tolerance (NGT) and associated with VAT inflammation, insulin resistance, and presence of adipocyte size heterogeneity." (PMID 33003532, 2020). "Glucocorticoid-induced glucose intolerance and insulin resistance was compromised in Angptl4−/− mice." (PMID 30310815, 2018). "In old, obese rats that showed signs of insulin resistance, the responses of ANGPTL4 and GPIHBP1 mRNA and of LPL activity were severely blunted (at 26 weeks of age) or almost abolished (at 52 weeks of age)." (PMID 23176178, 2012). "In multiple regression analysis, body mass index, homeostasis model assessment of insulin resistance, NGT vs. IGT, and NGT vs. NDD were independently associated with ANGPTL4 levels after adjustment for cardiovascular risk factors and adiponectin, whereas hepatic steatosis was not." (PMID 41226996, 2025). "Also, this group showed that levels of ANGPTL4 in the human serum have an inverse correlation with plasmatic glucose level and the homeostasis model assessment of insulin resistance." (PMID 38140923, 2023). "ANGPTL4 negatively correlates with circulating triglycerides and is linked with metabolic syndrome and T2D, whilst ANGPTL6 is elevated in T2D subjects and correlates with insulin resistance." (PMID 37810875, 2023). "ANGPTL4 expression is regulated by glucocorticoids, which increase over fasting in elephant seals, and may contribute to insulin resistance, which is also displayed by fasting elephant seals." (PMID 36589428, 2022). "Additionally, an upregulated expression of the pro-inflammatory gene Angptl4, which is supposed to increase insulin resistance, was observed; on the other hand, Irs1, a gene that improves insulin sensitivity, was downregulated." (PMID 36299624, 2022). "The enhancement of insulin resistance in the context of elevated ANGPTL4 levels could be explained by the selective inhibition of LPL in white adipose tissue, which leads to an ectopic lipid accumulation and insulin resistance." (PMID 30944669, 2019).
Insulin resistance (continued). "Therefore, glucose intolerance and insulin resistance were improved in exogenous glucocorticoid treated Angptl4−/− mice." (PMID 30310815, 2018). "These extra-articular conditions often accompany RA and also relate to insulin resistance, leading to suggestions that ANGPTL4 might represent a molecular link between insulin resistance and RA." (PMID 28458654, 2017). "In addition, administration of propolis suppressed the P. gingivalis-induced increased expression of Angptl4, a gene that is supposed to increase insulin resistance." (PMID 27576340, 2016). "In addition to proinflammatory genes, expression of Angptl4 which is involved in insulin resistance was also upregulated." (PMID 24797416, 2014). "This might indicate that the dietary-fat induced up-regulation of Angptl4 in the small intestine can provoke a systemic effect on development of insulin resistance." (PMID 18457598, 2008). "Additionally, insulin has been shown to down regulate angiopoietin-like 4 in adipocytes and this down-regulation could be attenuated in insulin resistance." (PMID 23320804, 2013). "ANGPTL4 expression is also stimulated by insulin sensitizing drugs thiazolidinediones via PPARy mediated mechanism suggesting that changes in ANGPTL level could have a role in the development of insulin-resistance." (PMID 22471940, 2012). "The intestinal flora of gut microbiota in obese Chinese children and adolescents with and without insulin resistance (IR) was analyzed, as well as associations between the gut microbiota and two serum cytokines related to glucose metabolism, adropin and angiopoietin-like 4 (ANGPTL4)." (PMID 33815293, 2021). "In rodents, HIF−1α upregulation starts early after the administration of a high-fat diet, before inflammation and insulin resistance develop, and HIF−1α induces ANGPTL4 expression, likely as a compensatory mechanism to limit adipocyte expansion." (PMID 33003532, 2020). "In this sense, we have found an upregulation of different genes related to hypoxia regardless of the degree of insulin resistance, such as ANGPTL4, LPL, S100A8, SLC11A2, HBB, HBA2, and HBD." (PMID 35625760, 2022). "VAT ANGPTL4 mRNA was not correlated with VAT LPL expression although increased LPL mRNA expression was associated with higher FSI (r = 0.46, p = 0.019) and insulin resistance (HOMA-IR: r = 0.44, p= 0.024)." (PMID 33003532, 2020). "A recent study, however, has demonstrated an improved glucose tolerance accompanied by an increased fat mass in Angptl4 knockout mice fed a diet high in saturated fatty acids, suggesting that an increase in LPL activity in the adipose tissue might prevent insulin resistance in these animals." (PMID 34440242, 2021). "Thus, the circulating levels of ANGPTL4 were significantly higher in the group of patients with T2D than in any other group, including those with MHO and MUO, with a pattern of changes reproduced exactly by the HOMA index of insulin resistance." (PMID 34440242, 2021). "VAT ANGPTL4 levels correlated negatively with high-density lipoprotein (HDL) cholesterol (r = −0.24; p = 0.048) and positively with fasting serum insulin (FSI) (r = 0.51; p= 0.008) and Homeostatic Model Assessment for Insulin Resistance (HOMA-IR) (r = 0.43; p = 0.029)." (PMID 33003532, 2020). "Moreover, ANGPTL-4 presented a negative correlation with BMI, waist circumference, weight, insulin, homeostasis model assessment of insulin resistance index (HOMA index), triglycerides, and leptin, and a positive correlation with FFA and vitamin-D." (PMID 31207920, 2019).
hypertriglyceridemia (41 papers, 2007 to 2026). A laboratory test result indicating elevated triglyceride concentration in the blood. "Recent studies have indicated that podocyte-secreted ANGPTL4 causes proteinuria, while circulating ANGPTL4 contributes to hypertriglyceridemia." (PMID 40968277, 2026). "Meanwhile, mice with ANGPTL3 and ANGPTL4 deficiency had severe hypertriglyceridemia while mice with ANGPTL3 overexpression had hyperlipidemia." (PMID 37170504, 2023). "Intravenous administration of recombinant human Angptl4 mutated to avoid hypertriglyceridemia and cleavage has remarkable efficacy in reducing proteinuria by as much as 65% for 2 weeks after a single low dose." (PMID 24611049, 2014). "By contrast, a sialylated circulating form of Angptl4, mostly secreted from skeletal muscle, heart and adipose tissue in all major primary glomerular diseases, reduces proteinuria while also causing hypertriglyceridemia." (PMID 24611049, 2014). "Transgenic overexpression of Angptl4 from a liver-specific promoter causes hypertriglyceridemia similar to that induced by adenoviral over-expression." (PMID 17949489, 2007). "Circulating ANGPTL4 also induces hypertriglyceridemia via lipoprotein lipase inhibition, and studies in rat models of diabetic nephropathy using injection of recombinant-mutated human ANGPTL4 have suggested that the antiproteinuric effect occurs at a lower dose than the hypertriglyceridemic effect." (PMID 37795536, 2023). "It was suggested that elevated levels of Angptl4 could contribute to hypertriglyceridemia, which is associated with inflammation; however, a direct effect of Angptl4 on inflammatory pathways has not been demonstrated so far." (PMID 26054961, 2015). "Overexpression of ANGPTL4 and injection of recombinant ANGPTL4 lead to hypertriglyceridemia in mice, whereas antibody-mediated inactivation, genetic silencing, and complete genetic ablation of ANGPTL4 significantly decrease plasma TG levels." (PMID 38431115, 2024). "The metabolic function of Angptl4 in regulating proteinuria and its relationship with hypertriglyceridemia in a mouse model of glomerular disease have been described previously." (PMID 39630889, 2024). "Finally, we considered the fact that ApoC2 is a critical activator of LPL activity as shown by the fact that ApoC2 deficiency results in severe hypertriglyceridemia and wondered what the effects of ANGPTL4/8-mediated plasmin generation might be on ApoC2-mediated stimulation of LPL activity." (PMID 37666362, 2023). "In Angptl4 knockout mice (Angptl4−/−), despite the administration of dexamethasone, the rate of hepatic steatosis and hypertriglyceridemia were significantly decreased." (PMID 35052872, 2022). "Only the link between hypertriglyceridemia and proteinuria, which was mediated by increasing circulating angiopoietin-like 4 levels, has been elucidated." (PMID 34587945, 2021). "Previous studies suggested that ANGPTL4 is a critical link between proteinuria and hypertriglyceridaemia." (PMID 34167540, 2021). "The increase in circulating ANGPTL4 promoted hypertriglyceridemia and decreased proteinuria in NS rats." (PMID 33853533, 2021). "Studies of transgenic mice showed that ANGPTL4 decreases blood glucose and improves glucose tolerance, at the same time, it induces hypertriglyceridemia and hepatic steatosis." (PMID 30049845, 2018). "Angiopoietin-like-4 (Angptl4) is a potent inhibitor of lipoprotein lipase and induces marked hypertriglyceridemia after intravenous injection or adenovirus-mediated expression." (PMID 26352670, 2015). "Recent research has demonstrated that podocyte-secreted Angptl4 induces proteinuria and circulating Angptl4 mediates hypertriglyceridemia." (PMID 26352670, 2015). "ANGPTL4-related LPL activity inhibition caused the inhibition of LPL-dependent VLDL lipolysis, leading to hypertriglyceridemia." (PMID 26690452, 2015).
hypertriglyceridemia (continued). "Previous work has demonstrated that circulating Angptl4 induced hypertriglyceridemia in PHN and PAN rat models, and our previous study reported that tacrolimus reduces serum triglycerides in a PHN rat model." (PMID 26352670, 2015). "Genes mapping to approved or investigational drugs included CALCRL (target of several medications used to manage migraine disorder), LAMC1 (target of ocriplasmin, used to treat vitreomacular traction), and ANGPTL4 (investigational target for hypertriglyceridemia)." (PMID 40874306, 2025). "The increase in circulating Angptl4 in response to nephrotic-range proteinuria reduces the severity of the disease phenotype; however, it induces hypertriglyceridemia, suggesting a potential link between circulatory Angplt4 with proteinuria and dyslipidemia in nephrotic syndrome." (PMID 39630889, 2024). "In addition, overexpression of ANGPTL4 decreased LPL activity, increased plasma TG levels, and triggered hypertriglyceridemia in a fasting mouse model, but the effect of ANGPTL4 was diminished during a long-term high-fat feeding program." (PMID 36837768, 2023). "Besides, it was reported in the previous study that ANGPTL4 can regulate the activity of lipoprotein lipase activity and hypertriglyceridemia." (PMID 37821811, 2023). "However, the beneficial effects of Angptl4 toward glucose metabolism were counteracted by increased hepatic steatosis, altered liver function profile, hypertriglyceridemia, and hypercholesterolemia, probably due to accompanying lipogenesis." (PMID 36292250, 2022). "Additionally, ANGPTL4 has been suggested as a link between hypertriglyceridemia and albuminuria in the nephrotic syndrome." (PMID 31772941, 2019). "We previously showed that chronic glucocorticoid treatment-induced hepatic steatosis and hypertriglyceridemia are attenuated in mice lacking angiopoietin-like 4 (Angptl4), a GR primary target gene that encodes a secreted protein that inhibits lipoprotein lipase and promotes adipose tissue lipolysis." (PMID 40490140, 2025). "Additionally, circulating ANGPTL4 induces hypertriglyceridemia by inhibiting LPL." (PMID 39840089, 2024). "But whether the level of hypertriglyceridemia and the use of fibrates influence the diagnostic value of ANGPTL4 have not been identified in present study." (PMID 37821811, 2023). "Lastly, it has been recently demonstrated that angiopoietin-like 4 (ANGPTL4, fasting-induced adipose factor), a primary downstream gene of GC receptor signaling pathway in both hepatocytes and adipocytes, is strictly linked with the GC-induced hepatic steatosis and hypertriglyceridemia." (PMID 35052872, 2022). "In the current study, we determined that tacrolimus improved defects in lipid metabolism, and we presumed that these findings were the result of tacrolimus-induced activation of a specific pathway that could inhibit hypertriglyceridemia and hypercholesterolemia via circulating Angptl4." (PMID 26352670, 2015). "ANGPTL4 can delay the clearance of TG in the circulation by inhibiting LPL, leading to hypertriglyceridemia." (PMID 32280690, 2020). "ANGPTL4 is known to inactivate LPL, which reduces triglycerides (TG) conversion to free fatty acids, leading to hypertriglyceridemia." (PMID 32638512, 2020). "In fact, ANGPTL4 is a potent irreversible inhibitor of lipoprotein lipase (LPL) activity, which leads to hypertriglyceridemia." (PMID 23947536, 2013). "Polyunsaturated fatty acids (PUFAs) have beneficial effects on hypertriglyceridemia although their effect on angiopoietin-like proteins (ANGPTLs), specifically ANGPTL3, ANGPTL4 and ANGPTL8 is unknown." (PMID 32153916, 2019). "For example, we did not evaluate angiopoietin-like 4 that links proteinuria with hypertriglyceridemia in nephrotic syndrome." (PMID 30384404, 2018).